PNKP (polynucleotide kinase 3'-phosphatase)
Description:
Plays a key role in the repair of DNA damage, functioning as part of both the non-homologous end-joining (NHEJ) and base excision repair (BER) pathways. Through its two catalytic activities, PNK ensures that DNA termini are compatible with extension and ligation by either removing 3'-phosphates from, or by phosphorylating 5'-hydroxyl groups on, the ribose sugar of the DNA backbone.
Synonyms: PNK; AOA4; CMT2B2; EIEE10; MCSZ
Tractability: PROTAC: ubiquitination databases record sites on it; its protein half-life has been measured; a small molecule that binds it is known.
Target class: Enzyme; Transferase
Gene: Protein-coding gene on chromosome 19 (49,859,882 to 49,878,351, reverse strand). Ensembl gene ENSG00000039650.
Subcellular location: Nucleus; Chromosome
Subcellular location (Human Protein Atlas): Nucleoli; Nucleoplasm
Pathways (Reactome):
DNA Repair: APEX1-Independent Resolution of AP Sites via the Single Nucleotide Replacement Pathway
Gene Ontology:
Molecular function: ATP-dependent polydeoxyribonucleotide 5'-hydroxyl-kinase activity; polynucleotide 3'-phosphatase activity; protein binding; ATP binding; damaged DNA binding; double-stranded DNA binding; endonuclease activity; purine nucleotide binding; ATP-dependent polynucleotide 5'-hydroxyl-kinase activity
Biological process: double-strand break repair via nonhomologous end joining; positive regulation of double-strand break repair via nonhomologous end joining; positive regulation of telomere maintenance; response to oxidative stress; base-excision repair; base-excision repair, gap-filling; DNA-templated DNA replication; nucleotide-excision repair; regulation of DNA repair; response to radiation; single strand break repair; DNA damage response; DNA repair
Cellular component: chromosome; membrane; nucleolus; nucleoplasm; nucleus; site of double-strand break; DNA ligase III-XRCC1 complex; site of DNA damage
Genetic constraint (gnomAD): Loss-of-function variants: 82 observed, 64.53 expected, observed/expected ratio (o/e) 1.27, 90% interval 1.06 to 1.53. The synonymous counts are far from expectation, so gnomAD's model fits this gene poorly and the ratio says little. Missense variants: 904 observed, 701.5 expected, observed/expected ratio (o/e) 1.29, 90% interval 1.22 to 1.36. Synonymous variants: 411 observed, 301.42 expected, observed/expected ratio (o/e) 1.36, 90% interval 1.26 to 1.48.
Gene-disease validity (ClinGen):
ClinGen rates the evidence that PNKP causes each of these diseases.
microcephaly, seizures, and developmental delay (autosomal recessive): Definitive.
Homologues: Orthologues: chimpanzee PNKP (99% identical), macaque PNKP (91% identical), dog PNKP (87% identical), pig PNKP (84% identical), guinea pig PNKP (83% identical), mouse Pnkp (81% identical), rat Pnkp (78% identical), tropical clawed frog dusp8 (56% identical), zebrafish pnkp (53% identical), Drosophila melanogaster PNKP (38% identical), Caenorhabditis elegans F21D5.5 (34% identical).
Diseases named in the same sentence as PNKP in open-access papers:
PNKP is named in the same sentence as 64 diseases in open-access papers, as found by Europe PMC text mining. Sharing a sentence is not in itself a finding about the gene and the disease. The quoted sentences say what the papers report.
microcephaly (30 papers, 2013 to 2025). A congenital or acquired developmental disorder in which the circumference of the head is smaller than normal for the person's age and sex. "For families with a history of microcephaly, particularly those with identified mutations in genes such as PNKP, it is essential to compile comprehensive medical histories." (PMID 39833032, 2025). "In this study, we describe two novel patients with developmental and epileptic encephalopathy (DEE) and severe microcephaly, both harboring compound heterozygous variants in the PNKP gene." (PMID 41283299, 2025). "This patient exhibited microcephaly, early-onset epilepsy, and developmental delay, reinforcing the association between PNKP variants and severe neurological outcomes." (PMID 41283299, 2025). "In this study, we report a patient with microcephaly, seizures, and intellectual disability and with compound heterozygous variants in the DNA repair gene, PNKP." (PMID 37916443, 2023). "In 2010, biallelic pathogenic PNKP variants were reported to cause “microcephaly, seizures, and developmental delay” (MIM# 613402)." (PMID 34697416, 2022). "Like congenital ZIKV infection, mutations in the polynucleotide 5′-kinase 3′-phosphatase (PNKP) gene, which encodes a critical DNA damage repair enzyme, result in recessive syndromes often characterized by congenital microcephaly with seizures (MCSZ)." (PMID 35412344, 2022). "In the present study, we show a link between ZIKV infection and the DNA damage repair enzyme PNKP, which is itself also linked to microcephaly." (PMID 35412344, 2022). "The patient was a 3-year-old male with a history of known PNKP mutations resulting in medically intractable epilepsy, global developmental delay and microcephaly." (PMID 35354845, 2022). "Biallelic PNKP variants cause heterogeneous disorders ranging from neurodevelopmental disorder with microcephaly/seizures to adult-onset Charcot–Marie–Tooth disease." (PMID 34697416, 2022). "The human orthologue of this gene is polynucleotide kinase 3’-phosphatase (PNKP), which is implicated in microcephaly, seizures and developmental delay and EIEE." (PMID 32899411, 2020). "AOA type 4 (AOA4) is caused by mutations in DNA repair factor polynucleotide kinase phosphatase (PNKP), which encodes for a DNA processing enzyme also involved in other syndromes featured by microcephaly or neurodegeneration." (PMID 32010037, 2020). "Many affected genes participated in brain-related diseases or disorders; for example, inactivation of PNKP causes brain dysplasias, such as microcephaly and cerebellar atrophy, while VPS53 is associated with cerebral and cerebellar atrophy." (PMID 30930929, 2019). "Some PNKP mutations cause an autosomal recessive disease characterized by microcephaly, seizures and developmental delay and behavioral problems (denoted MCSZ)." (PMID 31110700, 2019). "Consistent with our findings, point mutations in PNKP result in microcephaly and seizures, whereas a frame-shift mutation in the PNKP gene was identified in a neurodegenerative disorder characterized by epilepsy." (PMID 30994454, 2019). "The presence of a homozygous frame-shift mutation in PNKP was recently identified in an early-onset neurodegenerative disorder that manifests with polyneuropathy, cerebellar atrophy, microcephaly, epilepsy and intellectual disability." (PMID 25590633, 2015). "PNKP is mutated in microcephaly, early-onset, intractable seizures and developmental delay (MCSZ), in autosomal recessive manner." (PMID 24066114, 2013). "Variants in the PNKP (polynucleotide kinase 3’-phosphatase) gene have been linked to a spectrum of neurodevelopmental disorders characterized by epilepsy, cognitive impairment, and microcephaly." (PMID 41283299, 2025).
microcephaly (continued). "In fact, mutations in PNKP gene cause inherited diseases accompanying severe neural developmental failure, such as microcephaly and seizure (MCSZ), and neurodegeneration such as ataxia with oculomotor apraxia 4 (AOA4) and Charcot-Marie-Tooth disease 2B2 (CMT2B2)." (PMID 32970693, 2020). "Mutations in PNKP result in several diseases spanning a spectrum of neurological pathology, from neurodevelopmental dysfunction in microcephaly with early-onset seizures (MCSZ) through to moderate or mild/late-onset neurodegeneration in AOA4 and CMT2B2, respectively." (PMID 32504494, 2020). "Similarly, mutations in the DNA repair enzyme Ligase 4 result in microcephaly and inactivation of the DNA repair factor PNKP has been shown to cause seizures, microcephaly, oligodendrocyte dysfunction, and mutations in this gene lead to cognitive impairments and even severe dementia." (PMID 33964983, 2021). "Moreover, using genome-wide linkage analysis in consanguineous families of an autosomal recessive disease, multiple point mutations were identified in PNKP that result in neurological phenotypes characterized by microcephaly, intractable seizures, and developmental delay." (PMID 25590633, 2015). "A spectrum of neurological diseases, although rare, such as microcephaly with early-onset seizures, progressive cerebellar atrophy and polyneuropathy, and AOA4 are associated with mutations in different domains of PNKP." (PMID 37061005, 2023). "Recently, mutations in PNKP have been linked to microcephaly, seizures, developmental delay (MCSZ), and ataxia-ocular motor apraxia 4 (AOA4)." (PMID 37762489, 2023). "PNKP is an essential DNA damage repair enzyme which, like ZIKV infection, is also linked to microcephaly." (PMID 35412344, 2022). "Mutation to PNKP is the underlying cause of microcephaly with early onset seizures (MCSZ) and cerebellar degeneration in ataxia oculomotor apraxia-4 (AOA4)." (PMID 34899270, 2021). "Recessive microcephaly, seizures, and developmental delay (MCSZ MIM#613402) due to mutations in the DNA-repair enzyme encoded by PNKP has onset in infancy." (PMID 30755602, 2019). "Mutations in PNKP have been recently identified as the cause of microcephaly with seizures (MCSZ), a syndrome characterized by profound neurodevelopmental microcephaly and early-onset seizures." (PMID 26942017, 2016). "Biallelic loss-of-function mutations in PNKP cause an autosomal-recessive DNA repair disorder with a core phenotype of EIEE, developmental delay and microcephaly." (PMID 26993267, 2016). "Building on prior literature, our findings further reinforce the remarkable phenotypic heterogeneity associated with PNKP variants, ranging from severe early-onset epileptic encephalopathies to epilepsy without microcephaly." (PMID 41283299, 2025). "Microcephaly with early‐onset seizures (MCSZ) is a neurodevelopmental disorder caused by pathogenic variants in the DNA strand break repair protein, polynucleotide kinase 3′‐phosphatase (PNKP)." (PMID 37916443, 2023). "Microcephaly with early‐onset seizures (MSCZ) is a neurodevelopmental disorder caused by pathogenic variants in the DNA strand break repair protein, polynucleotide kinase 3′‐phophatase (PNKP)." (PMID 37916443, 2023). "Even though PNKP is central to DNA repair, there have been no reports linking PNKP mutations in a Microcephaly, Seizures, and Developmental Delay (MSCZ) patient to cancer." (PMID 35354845, 2022). "We present the first prenatal diagnosis of PNKP-related primary microcephaly." (PMID 34697416, 2022). "According to this, the instability of the encoding variants of PNKP rather than specific mutations causes both microcephaly and neurodegeneration." (PMID 31110700, 2019). "PNKP probably plays an equally important role in humans, as a rare autosomal recessive disease characterized by microcephaly, early-onset intractable seizures and developmental delay (denoted MCSZ) was traced to partial loss-of-function mutations in the PNKP gene." (PMID 28922417, 2017).
microcephaly (continued). "Along with a review of the literature, these two novel cases confirm the broad phenotypic spectrum of PNKP-associated disorders and underscore the importance of including PNKP in the genetic screening of patients presenting with developmental and epileptic encephalopathy (DEE) and microcephaly." (PMID 41283299, 2025). "The importance of PNKP is illustrated by the observation that mutations in this gene result in the hereditary neurological diseases microcephaly with early onset seizures (MCSZ) and ataxia oculomotor apraxia 4 (AOA4) (25, –, 27)." (PMID 28821613, 2017). "Nuclear PNKP depletion, like the one induced by ZIKV, may therefore be sufficient to induce neurodevelopmental defects and microcephaly." (PMID 35412344, 2022). "Furthermore, in mouse model, defect of PNKP, as well as XRCC1, in central nervous system result in massive DNA damage and apoptosis in neural progenitors leading to the neural developmental failure such as neurodegenerative disease and microcephaly." (PMID 32970693, 2020).
developmental delay (21 papers, 2013 to 2025). "Microcephaly, epilepsy, and developmental delay (MCSZ) is a rare neurodevelopmental disorder associated with autosomal recessive inheritance of mutations in the polynucleotide kinase 3’-phosphatase (PNKP) gene." (PMID 39833032, 2025). "Microcephaly with early-onset, intractable seizures and developmental delay (MCSZ) is a hereditary disease caused by mutations in PNKP." (PMID 31518347, 2019). "Microcephaly with early-onset, intractable seizures, and developmental delay (MCSZ) is a rare inherited neurological disorder caused by biallelic loss-of-function variants in the polynucleotide kinase/phosphatase (PNKP) gene, which encodes an enzyme critical for DNA repair." (PMID 41283299, 2025). "Also, four mutations in the codifying gene for the polynucleotide kinase/phosphatase (PNKP) have been described and linked to early-onset intractable seizures and developmental delay (MCSZ)." (PMID 35842432, 2022). "PNKP is a dual function 5 ́-DNA kinase and 3 ́-DNA phosphatase which if mutated results in human neurological disease characterized by progressive cerebellar ataxia and early onset seizures with developmental delay." (PMID 27965414, 2017).
Ataxia (20 papers, 2015 to 2025). Ataxia refers to impaired coordination of voluntary muscle movement. "Recent reports have shown that mutation at a conserved glutamine (Gln) in PNKP leads to late-onset ataxia with oculomotor apraxia type 4 (AOA4) in humans and embryonic lethality in pigs." (PMID 37061005, 2023). "Most of the mutated genes caused a spastic ataxia phenotype, but PNKP associated with either ataxia and neuropathy or AOA was also amongst the most frequent causal-genes." (PMID 35326432, 2022). "In this study, we found three genes (POLG, SETX, and PNKP) with various molecular functions, causing recessive ataxia and neuropathy." (PMID 35326432, 2022). "Two new mutations in the PNKP gene were detected in both sisters, confirming the diagnosis of ataxia with oculomotor apraxia." (PMID 33654647, 2021). "AOA4 is a rare autosomal neurodegenerative disorder characterized by ataxia, oculomotor apraxia, and peripheral neuropathy caused by mutations in PNKP." (PMID 31110700, 2019). "Another mutation in PNKP at the same position (Gln517Leufs*24) has been shown to cause ataxia (including polyneuropathy)." (PMID 30039206, 2018). "Mutations in PNKP are associated with the human inherited disease microcephaly and seizures (MCSZ), a neurodevelopmental disease, ataxia oculomotor apraxia 4 (AOA4), and Charcot–Marie–Tooth disease (CMT2B2), a neurodegenerative disease." (PMID 40146629, 2025). "The most frequent genes were those associated with spastic ataxia, ataxia, and neuropathy or AOA: SACS (4 families, 21.1%), KIF1C (2 families, 10.5%), and PNKP (3 families, 15.8%); the remaining genes were identified in single families only." (PMID 35326432, 2022). "Mutations in PNKP gene causes inherited diseases, such as microcephaly and seizure (MCSZ) by neural developmental failure and ataxia with oculomotor apraxia 4 (AOA4) and Charcot-Marie-Tooth disease 2B2 (CMT2B2) by neurodegeneration." (PMID 32970693, 2020). "There are four subtypes of ataxia with oculomotor apraxia (AOA): AOA1 [mutations in APTX and/or PNKP]; AOA2 [mutations in SETX]; AOA3 [mutations in PIK3R5]; AOA4 [mutations in PNKP]." (PMID 38161589, 2023). "Similarly, if reduced DNA 5′-kinase activity is a cause of cerebellar ataxia and neurodegeneration in PNKP-mutated disease our results implicate SSBs arising from abortive TOP1 activity in AOA4 and CMT2B2, because this is a major source of DNA breaks with 5′-hydroxyl termini." (PMID 32504494, 2020). "Finally, PNKP mutations were also identified recently in Charcot-Marie-Tooth disease 2B2 (CMT2B2), which is associated with mild axonal peripheral polyneuropathy and relatively late-onset cerebellar ataxia." (PMID 32504494, 2020). "Moreover, we show that PNKP mutations should be considered in the differential diagnosis of recessive and/or sporadic ataxia also in non-Portuguese populations." (PMID 27165045, 2017). "Mutations in multiple DNA replication and repair genes such as TCD1, PNKP, XRCC1, and APTX result in ataxia, highlighting the central role of this pathway in these overlapping disorders." (PMID 31230722, 2019). "Importantly, several DNA-end processing enzymes recruited by XRCC1 are mutated in human ataxias, such as the spinocerebellar ataxia with axonal neuropathy-1 (SCAN1; mutated in TDP1), ataxia oculomotor apraxia-1 (AOA1; mutated in aprataxin) and ataxia oculomotor apraxia-4 (AOA4; mutated in PNKP)." (PMID 30991935, 2019). "We therefore hypothesize that the accumulation of persistent DNA SBs due to lower PNKP activity triggers an intrinsic signaling event leading to dysregulated neuronal gene expression that impairs neuronal function, leading to neurodegeneration and the development of ataxia." (PMID 25633985, 2015).
epilepsy (7 papers, 2015 to 2025). A brain disorder characterized by episodes of abnormally increased neuronal discharge resulting in transient episodes of sensory or motor neurological dysfunction, or psychic dysfunction. "Subsequently, the NGS epilepsy gene panel identified two heterozygous PNKP variants: a missense variant, c.148C>G (p.Gln50Glu) in exon 2 (rs756746191), previously classified as pathogenic and a novel nonsense variant, c.742C>T (p.Gln248Ter) in exon 7, resulting in a premature stop codon." (PMID 41283299, 2025). "This discovery highlighted the critical role of PNKP in the pathogenesis of epilepsy and emphasized the importance of targeted genetic screening in affected individuals." (PMID 41283299, 2025).
Oculomotor apraxia (7 papers, 2018 to 2023). Ocular motor apraxia is a deficiency in voluntary, horizontal, lateral, fast eye movements (saccades) with retention of slow pursuit movements. "Interestingly, in one family with pathogenic variants in SETX and one in PNKP, oculomotor apraxia was not present." (PMID 35326432, 2022).
breast carcinoma (5 papers, 2020 to 2025). "More plausibly in view of PNKP function, tamoxifen treatment of breast cancer cells can be associated with induction of oxidative stress." (PMID 34226276, 2021). "Interestingly, we found a positive correlation between PNKP and GPX4 expression in all types of breast cancer including TNBC patients." (PMID 40743845, 2025). "Notably, stratification of breast cancer patients based on PNKP expression levels revealed a negative correlation between PNKP and MAP1LC3B, which encodes the LC3B autophagy protein." (PMID 40743845, 2025). "The elevated activity of the lysosomal/autophagy pathway in PNKP-depleted cells is also reflected by the expression profiles of breast cancer patients, particularly of TNBC, where a negative correlation exists between PNKP expression and the autophagic pathway." (PMID 40743845, 2025).
Cerebellar atrophy (5 papers, 2015 to 2023). Cerebellar atrophy is defined as a cerebellum with initially normal structures, in a posterior fossa with normal size, which displays enlarged fissures (interfolial spaces) in comparison to the foliae secondary to loss of tissue. "In addition, PNKP mutations are the cause of the neurodegenerative disease ataxia with oculomotor apraxia 4 (AOA4), which exhibits progressive cerebellar atrophy and ataxia oculomotor apraxia." (PMID 32504494, 2020).